ATP1A3 (ATPase Na+/K+ transporting subunit alpha 3)
Diseases named in the same sentence as ATP1A3 in open-access papers (continued):
Sharing a sentence is not in itself a finding about the gene and the disease.
Dystonia (61 papers, 2009 to 2025). An abnormally increased muscular tone that causes fixed abnormal postures. "The phenotypic spectrum associated with ATP1A3 mutations extends beyond classic AHC to include rapid-onset dystonia parkinsonism and other movement disorders." (PMID 40746648, 2025). "The range of symptoms in humans with ATP1A3 mutations is huge, from developmental brain malformation to late-onset dystonia, and mouse models also exhibit a wide range of phenotype manifestations." (PMID 39111836, 2024). "For example, mutation of ATPase Na+/K+ transporting subunit alpha 3 (ATP1A3) in humans is associated with rapid-onset dystonia-Parkinsonism and alternating hemiplegia of childhood." (PMID 35465097, 2022). "Rapid-onset dystonia-parkinsonism due to ATP1A3 gene mutations presents with acute or subacute dystonia associated with minor parkinsonian features." (PMID 34204464, 2021). "Mutations that impair ATP1A3 activity cause rapid-onset dystonia in humans and permanent neurological dysfunction." (PMID 29758010, 2018). "Atp1a3 mutations cause rapid-onset dystonia Parkinsonism, which leads to Parkinson’s-like symptoms appearing during early adulthood, often with concurrent emergence of psychiatric symptoms." (PMID 28893375, 2017). "Rapid-onset dystonia-parkinsonism (RDP) is a rare autosomal dominant disorder that is caused by mutations in the ATP1A3 gene and is characterized by an acute onset of asymmetric dystonia and parkinsonism." (PMID 27835968, 2016). "ATP1A3, the cause of rapid onset dystonia-parkinsonism and alternating hemiplegia of childhood, encodes the catalytic subunit of a Na+/K+ pump that is expressed in neurons and cardiac cells and that is involved in maintaining ionic gradients." (PMID 23775978, 2013). "Mutations in the ATP1A3 gene cause movement disorders characterized by dystonia." (PMID 39533828, 2025). "The majority (n=43) were carriers of heterozygous variants in genes linked to dominantly inherited dystonia genes (ATP1A3, GCH1, SGCE, KMT2B, THAP1, TOR1A, and VPS16), while only one carrier of a homozygous PLA2G6 variant and one of compound-heterozygous PTS variants were identified." (PMID 40672488, 2025). "However, a cohort study found that the rostro-caudal severity gradient was uncommon among ATP1A3 mutation carriers with at least mild symptoms of dystonia (7%)." (PMID 39145297, 2024). "ATP1A3 gene mutations can result in the rapid-onset dystonia-parkinsonism." (PMID 36249530, 2022). "This was demonstrated in HEK-293 cells expressing ATP1A3 mutations associated with a severe phenotype of microcephaly, developmental delay, and dystonia, indicating competition between exogenous mutant ATP1A3 (α3) and endogenous ATP1A1 (α1) so that their sum was constant." (PMID 33833732, 2021). "Mutations in ATP1A3 are primarily associated with rapid onset dystonia-parkinsonism." (PMID 23775978, 2013). "In addition to the originally identified phenotypes of rapid-onset dystonia-parkinsonism, alternating hemiplegia of childhood, cerebellar ataxia, areflexia, pes cavus, optic atrophy, and sensorineural hearing loss syndrome, ATP1A3 is linked to a wide range of primarily neurologic disorders." (PMID 38612382, 2024). "We have generated an ATP1A3 mutant mouse that displays motor impairments and a hyperexcitable motor phenotype compatible with dystonia." (PMID 39533828, 2025). "DYT/PARK-ATP1A3 (dystonia 12, DYT12, rapid-onset dystonia–parkinsonism, OMIM#128235) is an autosomal dominant disorder caused by pathogenic variants in ATP1A3, located on 19q13.2." (PMID 40724495, 2025). "For patients with acute and unexplained dystonia or bradykinesia, gene screening on ATP1A3 should be timely performed." (PMID 35978945, 2022). "In patients with acute and unexplained dystonia or bradykinesia, gene screening on ATP1A3 should be timely performed." (PMID 35978945, 2022).
Dystonia (continued). "Other genes found to be associated with isolated or combined dystonia include ANO3 (DYT24), TUBB4A (DYT4), GCH1 (DYT5a), TH (DYT5b), TAF1 (DYT3), PRKRA (DYT16), ATP1A3 (DYT12), SGCE (DYT11), KCTD17, and CACNA1A." (PMID 33051750, 2021). "In 3/52 (6%) of the EOA-patients with comorbid dystonia (TTPA, ATP1A3 and TUBB2A gene mutations), both observers had indicated that dystonia was severely present and that dystonia was presented as the main phenotype." (PMID 33255407, 2020). "Here we show that α3+/D801Y mice suffer from abrupt hypothermia-inducible dystonia that recapitulates the abrupt triggerable onset of symptoms in ATP1A3 patients." (PMID 28472154, 2017). "Very similar irregular firing was seen in both DCN and Purkinje cells in a pharmacological model of ATP1A3 dystonia (Dyt12)." (PMID 26705335, 2015). "Genotype-phenotype correlations are essential for surgical decision-making, as outcomes vary even within the same gene—for example, ATP1A3-related dystonia may respond differently depending on the clinical presentation." (PMID 40717768, 2025). "Two further reports suggested that GPi-DBS was ineffective in ATP1A3-related dystonia." (PMID 33488508, 2020). "For example, mutations in the gene ATP1A3, which is downregulated by HDAC4, cause a rare rapid-onset dystonia-parkinsonism and is linked to altering intracellular calcium levels, which could impact on the ER, the principal intracellular store of calcium." (PMID 30503143, 2019). "Mutations in ATP1A3 (also known as dystonia-12, DYT12) lead to RDP, which is a rare autosomal dominant movement disorder with variable penetrance, characterized by the abrupt start of dystonia with signs of parkinsonism." (PMID 24904274, 2014). "Similarly, knock-in of one of the AHC mutations, D801N (Atp1a3+/D801N; Mashl+/−; MGI 6162645), recapitulated many of the clinical features of AHC, including hemiplegia, dystonia, tremor, and seizures, as well as deficits in memory, gait, and motor coordination and control." (PMID 39111836, 2024). "In contrast, DYT-ATP1A3 dystonia (rapid-onset dystonia parkinsonism), caused by mutations in the ATP1A3 gene, is an example of a combined dystonia disorder where afflicted individuals appear to receive no benefit from DBS, although to our knowledge, only 5 such patients have been reported on so far." (PMID 31817799, 2019). "Additionally, likely pathogenic or pathogenic variants were found in ATP1A3 (n = 5) and GNAO1 (n = 1) for genes causing combined dystonia, as well as ACTB (n = 1), IRF2BPL (n = 1), SPR (n = 1), and TUBB4A (n = 3) for genes linked to dystonia with other neurological or systemic features." (PMID 40533913, 2025). "In the last decade, numerous genetic disorders have been reported to encompass in their phenotype recurrent episodes of dystonia and/or chorea (i.e., ADYC5, GCH1, and ATP1A3)." (PMID 40724495, 2025). "This is evidence that dystonia, a key symptom of both RDP and AHC, can be studied in some of the Atp1a3 mutant mice." (PMID 39111836, 2024). "The brain regions of interest were chosen based on ATP1A3 neuropathology and neuroanatomical sources of the complex motor loops (CSPTC and CbTC pathways) that mediate motor dysfunction in dystonia." (PMID 36779071, 2023). "The classical distinction is very hard to differentiate between isolated and combined dystonias since many genes have been shown to determine multiple dystonic presentations (e.g., ANO3, GNAL, ADCY5, and ATP1A3)." (PMID 36705216, 2022). "Initial genetic analysis showed that both single-gene and panel (dystonia) sequencing were not conclusive for the following genes: ATP1A3, PRKRA, CACNA1a, DYTPRI, DYT1, and DAT1." (PMID 41153421, 2025).
Dystonia (continued). "Notably, dystonia or Parkinson-related proteins are altered in the XDP MSNs proteome, including ATP1A3, COL6A3, GBA, GIGF2, HTRA2, MAP2, SNCA, and TORAIP2." (PMID 38042508, 2024). "Therefore, ATP1A3 testing also needs to be considered in patients with dystonia with mid-adult onset, limb onset, and no family history." (PMID 39145297, 2024). "Therefore, based on the development of genetic diagnostic technologies, we suggest the following changes in the diagnosis criteria: (I) unexplained acute onset; (II) dystonia (especially with prominent bulbar findings); (III) with or without bradykinesia; (IV) with ATP1A3 variant." (PMID 35978945, 2022).
alternating hemiplegia of childhood (45 papers, 2013 to 2026). A rare neurodevelopmental disorder characterized by recurrent episodes of hemiplegia and paroxysmal disturbances associated with persistent developmental delay and cognitive impairment. "Heterozygous mutations of the ATP1A3 gene, encoding the Na+,K+-ATPase α3 subunit, have been identified as the primary cause of Alternating Hemiplegia." (PMID 26501181, 2015). "ATP1A3 is highly expressed in neurons of the adult rodent brain and mutations in the gene have been implicated in three autosomal dominant Mendelian diseases, including alternating hemiplegia of childhood (AHC) type 2, CAPOS syndrome, and Dystonia-12." (PMID 31616254, 2019). "In Alternating Hemiplegia of Childhood (AHC), also associated with ATP1A3 mutations, flunarizine significantly reduced the frequency and severity of paroxysmal attacks and has become the most commonly used symptomatic treatment." (PMID 40710367, 2025). "Beyond cardiovascular implications, ATP1A3 mutations have been implicated in neurological disorders such as Alternating Hemiplegia of Childhood (AHC) and rapid onset dystonia-parkinsonism (RDP), conditions characterized by dysfunctional neuronal excitability." (PMID 40851957, 2025). "Pathogenic variants in ATP1A3, the gene encoding the α3 subunit of the Na+/K+-ATPase, cause alternating hemiplegia of childhood (AHC) and related disorders." (PMID 38804677, 2024). "Mutation in ATP1A3 cause alternating hemiplegia of childhood (AHC, OMIM:614820), which is a rare syndrome characterized by infantile onset of episodic hemi-or quadriplegia." (PMID 33287870, 2020). "While some ATP1A2 mutations can cause alternating hemiplegia of childhood (AHC), the majority of cases are caused by mutations in ATP1A3." (PMID 33126486, 2020). "Alternating Hemiplegia of Childhood (AHC) is caused by mutations of the ATP1A3 gene which is expressed in brain areas that include structures controling autonomic, gastrointestinal, gut motility and GABAergic functions." (PMID 32883312, 2020). "Mutations in the ATP1A3 gene cause Rapid Dystonia Parkinsonism (RDP, DYT12), as well as Alternating Hemiplegia of Childhood (AHC)." (PMID 27445835, 2016). "Missense mutations in ATP1A3 encoding Na+,K+-ATPase α3 are the primary cause of alternating hemiplegia of childhood (AHC)." (PMID 26463346, 2016). "Mutations in ATP1A3 cause Alternating Hemiplegia of Childhood (AHC) by disrupting function of the neuronal Na+/K+ ATPase." (PMID 25996915, 2015). "Recently, ATP1A3 mutations have been shown to be also associated with alternating hemiplegia of childhood (AHC), which is characterized by early paroxysmal events, developmental delay and later dystonia, ataxia, choreoathetosis and seizures." (PMID 24803225, 2014). "Recently, mutations in the ATP1A3 gene were found associated with another neurological disease, alternating hemiplegia of childhood (AHC), as well." (PMID 24236096, 2013). "Missense mutations in ATP1A3 encoding Na+,K+-ATPase α3 have been identified as the primary cause of alternating hemiplegia of childhood (AHC), a motor disorder with onset typically before the age of 6 months." (PMID 23527305, 2013). "Dominant missense mutations in ATP1A3, encoding a Na+, K+ ATPase α-3 subunit, can cause Alternating Hemiplegia of Childhood (AHC), but how these mutations lead to AHC remains unclear." (PMID 42079228, 2026). "Additionally, an ATP1A3 variant have been associated with a spectrum of neurological disorders which includes alternating hemiplegia of childhood (AHC) and rapid-onset dystonia-parkinsonism (RDP)." (PMID 39024300, 2024). "Mutations in ATP1A3 are also associated with alternating hemiplegia of childhood (AHC)." (PMID 24803225, 2014). "In support of this therapeutic strategy, a recent report showed that crossing a Atp1a3 mouse model (Myskin) for Alternating Hemiplegia of Childhood (AHC) with a mouse model overexpressing a WT Atp1a3 allele could rescue the mutant phenotype through increased α3 pump activity." (PMID 27199775, 2016).
alternating hemiplegia of childhood (continued). "Several movement-related disorders are associated with mutations in ATP1A3, the gene encoding the Na+/K+-ATPase α3 subunit, including rapid onset dystonia parkinsonism (RDP) and alternating hemiplegia of childhood (AHC)." (PMID 39533828, 2025). "The ATP1A3 gene has also been reported in two other clinical entities, alternating hemiplegia of childhood (AHC, AHC2, OMIM #614820) and rapid-onset dystonia Parkinsonism (RDP, DYT12, OMIM #128235)." (PMID 34692702, 2021). "Although the c.2452G > A mutation has not been reported before, different mutations of ATP1A3 are known to cause two other autosomal dominant neurological diseases: rapid-onset dystonia-parkinsonism (DYT12; OMIM: 128235) and alternating hemiplegia of childhood (AHC; OMIM: 614820)." (PMID 24468074, 2014).
Parkinsonism (39 papers, 2007 to 2025). Characteristic neurologic anomaly resulting from degeneration of dopamine-generating cells in the substantia nigra, a region of the midbrain, characterized clinically by shaking, rigidity, slowness of movement and difficulty with walking and gait. "We previously reported that ATP1A3 c.823G>C (p.Ala275Pro) mutant causes varying phenotypes of alternative hemiplegia of childhood and rapid-onset dystonia-parkinsonism in the same family." (PMID 39145297, 2024). "ATP2A3 is highly expressed in cerebellar Purkinje cells (Allen Brain Atlas) and is a member of the P‐type ATPase superfamily that includes the gene (ATP1A3) causally associated with rapid‐onset dystonia‐Parkinsonism (DYT12)." (PMID 29770609, 2018). "Mutations of the genes encoding the Na/K-ATPase a-subunit (ATP1A2 and ATP1A3) have been described in three distinct human neurological disorders: familial hemiplegic migraine, rapid onset dystonia Parkinsonism, and alternating hemiplegia of childhood." (PMID 28593511, 2017). "There is growing evidence that ATP1a3 mutations are involved in many pediatric neurological diseases such as alternating hemiplegia, sensorineural hearing loss syndrome or again rapid-onset dystonia-Parkinson and early infantile epileptic encephalopathy." (PMID 38796484, 2024). "Additionally, overexpression of both wild-type and mutant ATP1A3 influenced the expression of genes associated with the dopamine signaling pathway and Parkinson’s disease in zebrafish at the transcriptional level." (PMID 39145297, 2024). "Interestingly, the atp1a3 gene in humans has been previously associated with the rapid-onset dystonia-parkinsonism (RDP), which is characterized by the rapid development of dystonic spasms, dysarthria, dysphagia, and parkinsonism." (PMID 22563390, 2012). "As mutations in the Atp1a3 gene are known to be related to dyskinesia, epilepsies and Parkinson’s disease this could be a relevant finding in the context of other reports describing a connection between the loss of Adcy5 and movement disorders like dyskinesia or autism-like behavior." (PMID 33919448, 2021). "Moreover, the ATP1A3 mutations reported in the two conditions all differ, and most alternating hemiplegia of childhood mutations occur de novo, while rapid-onset dystonia-parkinsonism mutations are more often inherited." (PMID 24468074, 2014). "Also, we review the location of the mutations in the ATP1A3 protein of individuals with AHC, rapid-onset dystonia-parkinsonism (RDP) variants, and early infantile epileptic encephalopathy (variants with hemiplegic attack)." (PMID 39088707, 2024). "Concerning Parkinson’s Disease, it has been demonstrated that α-synucleins clusters could interact with ATP1a3, and their accumulation decreases ATP1a3 efficiency." (PMID 38796484, 2024).